RNU7-55P (RNA, U7 small nuclear 55 pseudogene)
Synonyms: HSU7.36; U7.55; HSU7.55; RNU7P4; U7
Gene: Small nuclear RNA gene on chromosome 8 (9,072,455 to 9,072,516, reverse strand). Ensembl gene ENSG00000239078.
Homologues: Orthologues: chimpanzee U7 (98% identical), macaque U7 (85% identical), rabbit U7 (85% identical), rabbit U7 (82% identical). Paralogues in human: U7 (90% identical), RNU7-188P (87% identical), RNU7-2P (85% identical), RNU7-34P (85% identical), RNU7-62P (85% identical), RNU7-65P (85% identical), RNU7-88P (85% identical), RNU7-172P (84% identical), RNU7-26P (84% identical), RNU7-30P (84% identical), RNU7-48P (84% identical), RNU7-70P (84% identical), and 142 more.